RTCB (RNA 2',3'-cyclic phosphate and 5'-OH ligase)
Description:
3'-5' RNA ligase, catalytic subunit of the tRNA-splicing ligase complex (tRNA-LC), which is involved in the enzyme-dependent maturation of intron-containing pre-tRNAs. Functions downstream of the tRNA-splicing endonuclease that removes introns, ligating the two generated halves via phosphodiester bond formation. The ligation reaction, which requires guanosine triphosphate (GTP) and Mn(2+), proceeds through three metal-dependent steps. The first step requires ZBTB8OS/Archease and involves the guanylylation of RTCB at its active site histidine, forming a covalent GMP-histidine intermediate. Before the second step, RTCB also hydrolyzes the 2',3'-cyclic phosphate (cP) at the 3' end of the 5' tRNA exon, typically generated by the tRNA-splicing endonuclease, producing a 3' phosphate. The covalently bound GMP is then transferred to this 3' phosphate to form an RNA(3')- P-P-(5')G intermediate. In the final step, the 5'-OH of the 3' exon attacks the activated 3' end of the 5' exon, forming a 3'-5' phosphodiester bond and releasing GMP. RTCB also functions in non-canonical, spliceosome-independent, cytoplasmic splicing of XBP1 mRNAs during the unfolded protein response (UPR). Upon endoplasmic reticulum (ER) stress, the endoribonuclease IRE1/ERN1 excises a short intron, generating free exon ends that are aligned by RNA-intrinsic, zipper-like stem-loop structures. These exon ends are then recognized and ligated by RTCB. This splicing event yields the active XBP1s transcription factor, which induces genes required to resolve protein folding defects in the endoplasmic reticulum.
Synonyms: C22orf28; HSPC117; TSLIG5; FAAP; DJ149A16.6
Tractability: Small molecule: a structure with a bound ligand is known. PROTAC: UniProt records ubiquitination sites on it; ubiquitination databases record sites on it; its protein half-life has been measured.
Target class: Enzyme; Ligase
Gene: Protein-coding gene on chromosome 22 (32,387,576 to 32,412,265, reverse strand). Ensembl gene ENSG00000100220.
Subcellular location: Nucleus; Cytoplasm
Subcellular location (Human Protein Atlas): Nucleoplasm; Cytosol; Vesicles
Pathways (Reactome):
Metabolism of RNA: tRNA processing in the nucleus
Gene Ontology:
Molecular function: protein binding; protein guanylyltransferase activity; RNA binding; RNA ligase (GTP) activity; vinculin binding; ligase activity, forming phosphoric ester bonds
Biological process: IRE1-mediated unfolded protein response; mRNA splicing, via endonucleolytic cleavage and ligation; RNA splicing, via endonucleolytic cleavage and ligation; tRNA exon ligation; tRNA splicing, via endonucleolytic cleavage and ligation; RNA processing
Cellular component: catalytic complex; cytoplasm; cytosol; nucleoplasm; nucleus; tRNA-splicing ligase complex; endoplasmic reticulum membrane; nuclear envelope
Genetic constraint (gnomAD): Loss-of-function variants: 19 observed, 44.85 expected, observed/expected ratio (o/e) 0.42, 90% interval 0.29 to 0.62. The upper end of that interval is the gene's LOEUF score, 0.62, which puts it in group 2 of 6, group 1 being the genes least tolerant of losing a copy. Missense variants: 414 observed, 544.74 expected, observed/expected ratio (o/e) 0.76, 90% interval 0.7 to 0.82. Synonymous variants: 199 observed, 189.19 expected, observed/expected ratio (o/e) 1.05, 90% interval 0.94 to 1.18.
Homologues: Orthologues: chimpanzee RTCB (100% identical), pig RTCB (100% identical), macaque RTCB (99% identical), mouse Rtcb (99% identical), rat Rtcb (99% identical), dog RTCB (96% identical), tropical clawed frog rtcb (95% identical), dog RTCB (94% identical), zebrafish rtcb (94% identical), rabbit BPIFC (90% identical), Drosophila melanogaster RtcB (85% identical), Caenorhabditis elegans rtcb-1 (73% identical).
Diseases named in the same sentence as RTCB in open-access papers:
RTCB is named in the same sentence as 13 diseases in open-access papers, as found by Europe PMC text mining. Sharing a sentence is not in itself a finding about the gene and the disease. The quoted sentences say what the papers report.
amebiasis (1 paper, 2021). A parasitic infectious disorder caused by amoebas. "Entamoeba histolytica, a protozoan parasite responsible for human amebiasis, possesses two RtcB proteins (EhRtcB1 and 2), but their biological functions remain unknown." (PMID 34976851, 2021).
breast carcinoma (1 paper, 2023). "RtcB has been shown to mediate resistance to antioestrogen treatment in MCF7 breast cancer cells." (PMID 37935993, 2023). "Similar to what was shown in breast cancer, a negative correlation was also found between miR-34a and RtcB expression in HNC tissues from The Cancer Genome Atlas (TCGA) database." (PMID 37935993, 2023).
glioma (1 paper, 2022). A benign or malignant brain and spinal cord tumor that arises from glial cells (astrocytes, oligodendrocytes, ependymal cells). "MRE11, RTCB, TIMM9 and METTL14 were up‐regulated in gliomas, while CDPIT and MFN2 were down‐regulated." (PMID 35044082, 2022).
melanoma (1 paper, 2022). A malignant, usually aggressive tumor composed of atypical, neoplastic melanocytes. "And in some cancers, the expression of YY1 is affected by mutations in certain genes; for example, in melanoma, the expression of YY1 is reduced by NOX3 and RTCB mutations." (PMID 35791393, 2022). "In melanoma, NADPH oxidase 3 (NOX3) and RNA 2',3'-cyclic phosphate and 5'-OH ligase (RTCB) mutations reduce YY1 expression." (PMID 35791393, 2022).
cancer (7 papers, 2020 to 2025). A tumor composed of atypical neoplastic, often pleomorphic cells that invade other tissues. "Finally, observations of the role of RtcB in multicellular organisms indicate a role in neurobiology, immunology and cancer, three areas linked to dysregulation of ER homeostasis." (PMID 37935993, 2023). "This analysis is followed by a description of the mechanisms regulating RtcB activity and localisation, its known partners and its various functions from bacteria to human with a specific focus on human cancer." (PMID 37935993, 2023). "Although this observation is not surprising due to the direct involvement of RtcB ligation activity on XBP1, it highlights the potential of RtcB as a therapeutic target especially in cancer." (PMID 37935993, 2023). "Taken together, these studies show that the role of RtcB impacts various fields such as neurology, immunology and cancer." (PMID 37935993, 2023). "Here, we summarise what is known about the consequences of RtcB activity in various biological systems, from bacteria to human cells and finish by examining the potential of RtcB as a therapeutic target in human cancer." (PMID 37935993, 2023). "Two independent studies identified RtcB as a target of miR-34a in cancer." (PMID 37935993, 2023). "Several lines of evidence support a potential role for RtcB in human cancer, and thus it may have value as a therapeutic target." (PMID 37935993, 2023). "To unravel the target gene of miR-34a that participated in the anti-cancer effects, we used bioinformatics software (Target Scan program) and predicted that RTCB may be a potential target." (PMID 32610494, 2020). "Finally, as relatively little is known regarding the role of RtcB in pathological conditions, we discuss what can be learned about the various roles of RtcB from bacteria to human cells and how this information reveals the potential and challenges of RtcB as a therapeutic target for human cancer." (PMID 37935993, 2023). "Regardless of these challenges, it is clear that RtcB may play hitherto unsuspected roles in cancer that are worthy of further investigation." (PMID 37935993, 2023).
tumor (6 papers, 2018 to 2023). "Consistent with this, mouse xenografts confirmed the anti-tumour effect of targeting RtcB, as the tumour volume and weight were reduced in a dose-dependent manner." (PMID 37935993, 2023). "In this study, we demonstrated that the inhibitory effect of miR-34a on tumor regeneration, metastasis, and clonogenic expansion was due to the downregulation of RTCB." (PMID 32610494, 2020). "We showed that the administration of genistein retarded tumor growth and upregulated the expression of miR-34a in the excised tumors with downregulated expression of RTCB." (PMID 32610494, 2020). "Furthermore, we showed that RTCB was a novel target that was negatively regulated by miR-34a and involved in the tumor repressive effect of genistein." (PMID 32610494, 2020). "Further analysis from patient samples confirmed that protein aggregation could predict tumour sensitivity to therapy, as RtcB showed lower co-localisation with aggresomes in the metastatic versus primary tumours prior to antioestrogen treatment, confirming a role for RtcB in treatment resistance." (PMID 37935993, 2023). "Indeed, it is likely that in XBP1+/RIDD− tumors, inhibition of IRE1 RNase with small molecules or selective inhibition of the XBP1 mRNA ligase RtcB might lead to significant impairment of tumor growth." (PMID 29311133, 2018).
infection (2 papers, 2021 to 2025). The state of being infected such as from the introduction of a foreign agent such as serum, vaccine, antigenic substance or organism. "These pulldowns also verified that TOP2B associates with DDX1, FAM98A, and RTCB, suggesting a potential role for this isoform in RNA metabolism during infection." (PMID 40557872, 2025). "Considering that the expression patterns of genes are often different under in vitro and in vivo conditions, our future work will focus on validating the role of RtcB in the pathogenicity of the bacterium by in vivo infection assays using P. aeruginosa rtcB deficient strains." (PMID 34830443, 2021). "To enhance the formation of AVGs, we silenced the expression of E3 and assessed the localization of DDX1, FAM98A, and RTCB at 6–8 h post infection." (PMID 40557872, 2025). "Next, we performed a eukaryotic (plant) infection assay to validate the functionality of H2-T6SS and H3-T6SS by deletion of rtcB." (PMID 34830443, 2021).
RTCB also shares sentences with these, for which no sentence is quoted: adenoma (1 paper); autism (1); bipolar disorder (1); Co-infection (1); myeloid leukaemia (1); retinitis pigmentosa (1).